CD4 (CD4 molecule)
Diseases named in the same sentence as CD4 in open-access papers (continued):
Sharing a sentence is not in itself a finding about the gene and the disease.
osteosarcoma (continued). "In our study, the phenotype of TIL isolated from adult osteosarcomas are very similar in all cases (two third of CD4+ and one third of CD8+) and autologous PBL were weakly cytotoxic against the four allogeneic cell lines tested." (PMID 16188028, 2005). "A primary canine osteosarcoma specimen before any therapy was characterized, showing significant genomic instability and chromosomal copy number variations, as well as clusters of osteoblasts, fibroblasts, endothelial cells, myeloid cells, and CD4+ T cells." (PMID 40563676, 2025). "Additionally, five key genes, including CD4, RUNX2, OMD, COL9A3, and JUN, were found to be associated with osteosarcoma progression." (PMID 39324133, 2024). "On the other hand, studies on a mouse model using osteosarcoma cell line AX have shown that TNF by tumor-associated macrophages and IL-17 produced by CD4+ lymphocytes maintain osteosarcoma cells in an undifferentiated state by inhibiting their osteoblastic differentiation." (PMID 39060500, 2024). "Thus, the knockout of mGluR4 in DCs increases the expression of IL-23 which is a pro-tumor cytokine in the osteosarcoma model, while the deletion of mGluR4 in CD4, CD8 T, and NK cells improves the immune response and decreases the tumor growth." (PMID 36817470, 2023). "However, the CD4 + /CD8 + ratio was decreased significantly in patients with osteosarcoma compared to GCT tumors (P = 0.01)." (PMID 37993664, 2023). "However, Pearson analysis demonstrated that BAP1 was negatively correlated with the fraction of naïve CD4 T cells in osteosarcoma tissues." (PMID 36003792, 2022). "PD-1 blockade reportedly decreased CD4 Tregs: Teffs ratios in TILs of a murine osteosarcoma model." (PMID 35449134, 2022). "Compared with normal bone tissues, the infiltration proportions of plasma cells (p = 0.003) and naïve CD4 T-cells (p = 0.001) were significantly reduced in osteosarcoma tissues, while the infiltration proportions of M0 macrophages (p = 0.012) and M2 macrophages (p = 0.006) were increased." (PMID 35463956, 2022). "Vincristine, dexamethasone, and vinblastine may form a promising drug–target pair with RUNX2, OMD, and CD4 for Osteosarcoma treatment." (PMID 36686663, 2022). "In osteosarcoma, CD28 expression is significantly associated with activated memory CD4 T-cells." (PMID 35463956, 2022). "We conferred that the high expression of PLOD2 in osteosarcoma may repress immune cell infiltration, especially CD4 and CD8A T cells." (PMID 36276118, 2022). "In patients with TCGA osteosarcoma, CIBERSORT analysis showed that the low-risk group had a higher proportion of T-cells CD8 and T-cells CD4 memory activated, while a lower proportion of T-cells CD4 naive when compared with the high-risk group." (PMID 36569871, 2022). "Interleukin 17 was a CD4+ T cell-derived cytokine that stimulated some tumor cells to secrete angiogenesis factor, and the IL-17 receptor might represent a marker for the osteosarcoma metastasis." (PMID 36466554, 2022). "OLMALINC may affect osteosarcoma development by inhibiting memory B cell proliferation and function, recruiting mast cells, and naive CD4+ T cells." (PMID 35494024, 2022). "Notably, we noticed a CD4+ T cell sub‐cluster CD4_ C5_KLRB1 cells presented strong cytotoxicity in osteosarcoma TME." (PMID 36305631, 2022). "Furthermore, we found that the levels of T cells CD8, T cells CD4 memory activated, macrophages M1 and macrophages M2 were markedly higher in osteosarcoma than normal tissues." (PMID 33748161, 2021). "In the present study, we used osteosarcoma specimens from cases treated at our hospital to investigate and characterize the relationship between clinical factors and the expression status of PD-1/PD-L1 immune checkpoint proteins, including CD4 and CD8." (PMID 32751195, 2020).
osteosarcoma (continued). "A recent study reported that high levels of PD-1 expression on peripheral CD4+ and CD8+ T cells were observed in patients with osteosarcoma, and the expression levels of PD-1 on CD4+ T cells in patients with metastasis were significantly higher than those without metastasis." (PMID 30693030, 2019). "An increased PD-1 expression on peripheral CD4+ T cells was also observed in patients with metastases, strengthening the idea that PD-L1/PD-1 axis may play a role during osteosarcoma progression." (PMID 27853827, 2017). "Similarly, TIL from osteosarcomas were predominantly CD4+ (median: 49.9%) with second highest CD8+ sub-population (median: 15.5%)." (PMID 16188028, 2005). "Therefore, promoting the proliferation and activation of memory CD4 T cells may be a strategy for improving osteosarcoma prognosis." (PMID 35463956, 2022). "Interestingly, NECTIN2–TIGIT interaction was enriched in proliferating TAMs and CD4_C3_CXCL13, CD4_C3_FOXP3 and CD8_C2_GNLY cell sub‐clusters, indicating that Proli_TAM may lead to T cell exhaustion in osteosarcoma PT tissues." (PMID 36305631, 2022). "Results of CIBERSORTx B-mode on gene expression profiles of 141 osteosarcoma patients (cohorts 1 and 2) demonstrates that M0 Macrophages is the most frequent immune cell in osteosarcoma tumors with an average of 40% of total immune cells, followed by M2 Macrophages and CD4 T cells." (PMID 33757216, 2021). "The combination further increased CD4+ and CD8+ recruitment, shifted CD4+ naïve T cells to CD4+ effector memory cells, and rendered a higher efficacy compared to TRB alone, preventing osteosarcoma progression." (PMID 38257245, 2024). "The study of the heterogeneity and immunosuppressive function of Tregs in naïve primary osteosarcoma demonstrated greater Treg infiltration than in normal bone, with a positive expression of FOXP3, CD4, CTLA-4, and TIGIT in Tregs." (PMID 39359731, 2024). "A similar approach was conducted in murine osteosarcoma models where TRB inhibited osteosarcoma primary tumour growth and metastasis and enhanced the number of T-cell tumour-infiltrated cells (both CD4+ and CD8+)." (PMID 38257245, 2024). "And the result showed that SGLT2 inhibitor treatment further inhibited the tumor growth and promoted the infiltration of CD4+ and CD8+ T cells induced by immunotherapy (anti-PD-1) therapy in osteosarcoma." (PMID 35662245, 2022). "They found that the PD-1/PD-L1 immune checkpoint system, involving CD4 and CD8, plays an important role in the pathogenesis of osteosarcoma." (PMID 35292660, 2022). "Collectively, these results suggested that the expression of the c-Myc oncogene is negatively correlated with the abundances of CD4+ and CD8+ tumor-infiltrating lymphocytes (TILs) in human osteosarcoma." (PMID 35292660, 2022). "Using multiplex fluorescence staining methods, we observed co‐localization of CD4+FOXP3+ Tregs and LAMP3+ DC in osteosarcoma tissues, which indicated the recruitment of Tregs by LAMP3_DC as previous reports." (PMID 36305631, 2022). "In a recent study, Kazuhiko Hashimoto and colleagues surveyed and characterized the expression of CD4, CD8, PD-1, and PD-L1 in osteosarcoma cases in detail." (PMID 35292660, 2022). "Next, we performed IHC staining to examine the expression of c-Myc, CD4, and CD8 in a cohort of 80 human osteosarcoma specimens." (PMID 35292660, 2022). "In contrast, positive staining for CD4 and CD8 was detected only in a small proportion of osteosarcoma tissues (37.5% and 27.5%, respectively), supporting the notion that osteosarcoma tumors are mainly immunologically “cold”." (PMID 35292660, 2022). "The expression of CD4, OMD, and JUN was decreased in Osteosarcoma cells compared with osteoblasts, whereas RUNX2 and COL9A3 expression was increased." (PMID 36686663, 2022). "TIM-3 upregulation in CD4+ and CD8+ peripheral T cells was found to correlate with the presence of osteosarcoma." (PMID 34940257, 2021).
osteosarcoma (continued). "Another study of osteosarcoma in rats showed increased IFN-γ+ cells in the spleen and increased CD3+ T, CD4+ T, and CD4+/CD8+ T cells as well as decreased levels of IL-2R in the peripheral blood." (PMID 35069599, 2021). "In our analysis, macrophage (M0, M1 and M2) is the majority infiltration in osteosarcoma while CD8 + T cell, CD4 + naïve T cell and follicular helper T cell are related to survival outcome." (PMID 32820615, 2020). "CD4-positive and CD8-positive TILs are thought to have similar contributions to tumor immunity in osteosarcoma." (PMID 32751195, 2020). "The next survival analysis of immune cell infiltration showed that T cell CD8, T cell CD4 naive and T‐cell follicular helper were related to the OS or PFS of patients with osteosarcoma." (PMID 32820615, 2020). "Evidence reveals that the percentage of PD-1 is significantly upregulated on both peripheral blood CD4+ and CD8+ T lymphocytes from osteosarcoma patients and PD-1 is involved in the progression of osteosarcoma." (PMID 27683579, 2016). "Ghost cell lines (Human osteosarcoma cells) expressing CCR5, CXCR4 with CD4 or CD4 alone (received from NIH AIDS Reagent Program) were used to determine co-receptor use." (PMID 19939258, 2009). "While TIL with a main CD4+ profile were easily isolated from most of the tumor samples, only TIL extracted from osteosarcoma were cytotoxic against allogeneic tumor cells." (PMID 16188028, 2005). "Hence, future studies should prioritize exploring strategies to enhance MHC-II expression or increase the presence of CD4 + and CD8 + T cells in the context of osteosarcoma." (PMID 39033089, 2024). "The expression of mGluR4 was detected at a very low level in CD4+ T cells in the mouse model of osteosarcomas, but not in CD8 T and NK cells." (PMID 36817470, 2023). "Importantly, our study showed that 2’3’-cGAMP promoted the infiltration of CD4+ and CD8+ T cells in osteosarcoma." (PMID 35662245, 2022). "Given the up-regulation of STING expression induced by the SGLT2 inhibitor, we also found that the combined treatment with SGLT2 inhibitor and 2’3’-cGAMP further promoted the infiltration of CD4+ and CD8+ T cells, exerting synergistic antitumor effects in osteosarcoma." (PMID 35662245, 2022). "The results showed that the abundances of CD4+ and CD8+ cells inside tumors were dramatically increased after JQ-1 administration, indicating that pharmacological inhibition of c-Myc can enhance T cell infiltration in osteosarcoma." (PMID 35292660, 2022). "Given that c-Myc inhibition exerted antitumor effects by enhancing T cell infiltration and activation, we then asked whether CD4+ and CD8+ T cell subsets play pivotal roles in the combination treatment of osteosarcoma." (PMID 35292660, 2022). "A weak negative correlation between C3AR1 expression and T cells CD4 naïve levels was found among osteosarcoma samples (r = −0.26; p = 0.0017)." (PMID 33748161, 2021). "There was a weak negative correlation between C3AR1 expression and T cells CD4 naïve levels in osteosarcoma samples." (PMID 33748161, 2021). "Moreover, programmed cell death protein 1(PD-1) showed increased expressed in TIL and peripheral CD4+ and CD8+ T-lymphocytes Based on this result, the inhibition of the PD-1/PDL-1 interaction would lead to a decreased tumor burden in osteosarcoma-bearing mice." (PMID 31992246, 2020). "Hence, the infiltration of Th1 CD4 + T cells and CD68 + macrophages in tissues is the key to affecting the efficacy of neoadjuvant chemotherapy and prognosis in osteosarcoma patients." (PMID 32850346, 2020). "Our in vivo experiments demonstrated that nivolumab inhibited lung metastasis of osteosarcoma rather than primary tumor growth by increasing the numbers of CD4+ and CD8+ lymphocytes as well as cytolytic activity of CD8 lymphocytes in the lung." (PMID 29409495, 2018).
osteosarcoma (continued). "In addition, it was also found that the fraction of CD4+CXCR5+Tfh cells in patients with metastasis of osteosarcoma was greater than in patients without metastasis." (PMID 35494526, 2022). "Within the scRNA-seq information for osteosarcoma (GSE162454), HSPD1 was detected in both cancerous cells and non-cancerous cells like endothelial cells, CD4+ T conventional lymphocytes, macrophages, and plasmocytes." (PMID 39430254, 2024). "scRNA-seq analysis of osteosarcoma tissues revealed that CD4-/CD8- (double negative; DN) T cells were one of the major types of lymphocytes, frequently observed in TILs of primary and advanced osteosarcoma tissues." (PMID 39359731, 2024). "Clonal cells were mostly identified in CD8+ T cells rather than CD4+ T cells, suggesting that the activation of CD8+ T cells plays vital roles in anti‐tumour activities of osteosarcoma." (PMID 36305631, 2022). "Nivolumab inhibited osteosarcoma metastasis in humanized mice by increasing CD4+ and CD8+ lymphocytes and the cytolytic activity of CD8 lymphocytes in the lung but did not affect primary osteosarcoma growth." (PMID 29409495, 2018). "Previous studies have indicated that NETs-related genes play a significant role in osteosarcoma metastasis and immune cell infiltration, with notable differences in key immune components, such as natural killer T (NKT) cells and CD4 T cells, observed between metastatic and non-metastatic groups." (PMID 40276062, 2025).
Parkinson disease (84 papers, 2012 to 2026). A progressive degenerative disorder of the central nervous system characterized by loss of dopamine producing neurons in the substantia nigra and the presence of Lewy bodies in the substantia nigra and locus coeruleus. "CD4+ cytotoxic T cells are also implicated in the pathogenesis of Parkinson’s disease and other neurodegenerative diseases drawing a direct corollary to NINTs especially MNTs." (PMID 41282927, 2025). "Gene set enrichment analysis associated CD4 with neurodegenerative pathways (e.g., Parkinson’s disease: normalized enrichment score = 1.57, p = 0.002) and oxidative phosphorylation (normalized enrichment score = 1.89, p = 7.4 × 10 − 6)." (PMID 41329689, 2025). "Recent single-cell transcriptome sequencing studies of peripheral blood mononuclear cells from Parkinson’s disease patients have shed light on the involvement of PD-associated peripheral CD4+ T cells in BBB impairment." (PMID 39135084, 2024). "CD4+ memory and cytotoxic T cells have also been shown to be associated with patients with Parkinson’s disease, suggesting a degree of specificity in T cell changes to different neurodegenerative diseases." (PMID 38867294, 2024). "In this regard, recent case–control association studies in Chinese and Caucasian Spanish populations showed a marginal association between CD4 rs1922452 and CD4 rs951818 single nucleotide variants (SNVs) and the risk for Parkinson’s disease." (PMID 39769168, 2024). "Two recent case–control association studies in different populations have shown an association between CD4 rs1922452 and CD4 rs951818 and the risk of Parkinson’s disease." (PMID 36674807, 2023). "Recent studies suggest that loss of CD4+ T-cells reduces dopaminergic cell death and microglia activation in a mouse model of Parkinson's disease, a chronic neurodegenerative condition." (PMID 32174913, 2020). "CD4+ T cells are recruited early and linked to protection of neurons in models of axotomy, Parkinson’s disease and ALS, while CD8+ T cells are present in affected tissue in end-stage disease in ALS and respond mainly to injury." (PMID 25889790, 2015). "Previous work showed that DAR3-deficient CD4+ T cells mount impaired Th1 responses and fail to induce neurodegeneration in a murine Parkinson’s disease model." (PMID 24711809, 2014). "CD4+ genes inversely associated with the PRS for Parkinson’s included DOCK8 and CD59." (PMID 38590520, 2024). "Two recent case-control association studies, one in a Chinese population and the other in a Caucasian Spanish population, have shown a weak, though significant, association between CD4 rs1922452 and CD4 rs951818 single nucleotide variants (SNVs) and the risk for Parkinson’s disease (PD)." (PMID 36499121, 2022). "D3R-deficient mice were observed to be protected against the loss of dopaminergic neurons and microglial activation during MPTP-induced Parkinson's disease; however, upon transfer of wild-type CD4+ T cells, mice became susceptible to MPTP-induced neuronal degeneration and activation of microglia." (PMID 26095429, 2015). "The results showed that CD4 gene was positively correlated with 19 pathways such as Alzheimer’s disease, Parkinson’s disease, and Huntington’s disease and so on." (PMID 41329689, 2025). "There were significant differences in the number of naive B cells, memory B cells, naive CD4 + T cells, regulatory T cells (Tregs), etc., between Parkinson’s patients and healthy controls." (PMID 41329689, 2025). "A recent investigation has revealed that CD4+ T cells from patients with Parkinson's disease (PD) specifically respond to antigenic MHC class II epitopes derived from α-synuclein." (PMID 38317227, 2024). "Further, IL-17 producing CD4+ T cells triggered neuronal death in a human iPSC model of Parkinson’s disease." (PMID 37435496, 2023).